INS (insulin)
Diseases named in the same sentence as INS in open-access papers (continued):
Sharing a sentence is not in itself a finding about the gene and the disease.
diabetes (continued). "Neither diabetes mellitus, nor multivitamin treatment had a significant effect on serum insulin levels in female animals." (PMID 25160946, 2014). "Patients with compensated as well as newly diagnosed thyroid disorders required significantly earlier insulin therapy compared to patients without thyroid diseases at the time of diabetes onset." (PMID 24580798, 2014). "The high proportion of study patients with diabetes suggests that physicians were more likely to use eProtocol-insulin in diabetic than non-diabetic patients." (PMID 24886864, 2014). "Using latent class trajectory analysis, we identified different weight gain trajectories in six age and sex strata, and used multivariable general linear mixed effects models to assess elevated metabolic markers of diabetes (fasting glucose, HbA1c, HOMA-IR, insulin) across weight trajectory classes." (PMID 24891020, 2014). "In an earlier study of GDM pregnancies (22% insulin treated; 78% diet controlled; no record of maternal BMI), it was found that compared to pregnancies not complicated by diabetes, the expression and activity of GLUT1 was unaltered." (PMID 25222554, 2014). "Some of these monoclonal antibodies have been shown to mimic insulin action in vitro, but they have not been tested in animal models of diabetes." (PMID 24533136, 2014). "It has been shown that in the neonatal thymectomy NOD model of T1D, gut intraepithelial CD8+γδ T cells can prevent development of diabetes, and proper development of intraepithelial γδ T cells is required for induction of regulatory CD4+CD25+ T cells by oral insulin." (PMID 24728138, 2014). "The Outcome Reduction with an Initial Glargine Intervention (ORIGIN) trial showed exactly the same number of cancer cases with glargine treatment vs. standard care without insulin treatment over 6 years in subjects with prediabetes or early diabetes." (PMID 25329887, 2014). "This study showed that both inflammation and glucocorticoids affect insulin secretion and sensitivity but this did not lead immediately to the development of hyperglycemia and type 2 Diabetes Mellitus." (PMID 25181348, 2014). "Diabetes occurs when the pancreas does not produce enough insulin, or when the body cannot effectively use the insulin produced." (PMID 24708659, 2014). "The effects of diabetes on degenerative and CVD may accelerate onset of MCI, as insulin-related effects may affect cognitive function." (PMID 24550827, 2014). "Diabetes mellitus type I (DM1), also known as insulin-dependent diabetes mellitus (IDDM), is a chronic autoimmune disease clinically characterized by hyperglycemia, resulting from the destruction of insulin-producing pancreatic β cells due to autoreactive T cells." (PMID 25157497, 2014). "In this study by using the in-silico approach we have found some potential inhibitors against SFRP4, which in the future may pave the way for diabetes mellitus cures by decreasing the expression of SFRP4 and increasing insulin production." (PMID 25019556, 2014). "This is because it would be unethical and unacceptable to compare insulin therapy with no treatment in people with uncontrolled diabetes." (PMID 25341370, 2014). "A further 9% of patients had fasting glucose concentrations in the diabetes range and were currently not prescribed oral hypoglycaemics or insulin." (PMID 25361884, 2014). "Some key covariates like age, gender and mean follow-up daily insulin dose were available, but many others like smoking, diabetes duration, HbA1c and body mass index were not." (PMID 24667573, 2014). "Quantification of beta cell function through arginine/glucose stimulation determined that as expected, individuals with a shorter time since diagnosis of diabetes and that required no insulin have relatively preserved beta cell function (metformin group only)." (PMID 25226365, 2014). "Survival was even shorter if the diabetes treatment strategy included insulin compared to patients without insulin therapy." (PMID 24447406, 2014).
diabetes (continued). "Patients receiving insulin treatment are more likely to take the disease more seriously, and are more likely to be symptomatic while non-insulin treated Type 2 persons with diabetes are usually asymptomatic." (PMID 24834373, 2014). "And although both insulin sensitivity and insulin secretion tend to decline with ageing, in our cohort, ageing and duration of diabetes were not independently related to PI/I ratio." (PMID 25347846, 2014). "BIT items commonly refer to the physical aspects of insulin use or technical concerns (e.g. side effects, pain) rather than the symbolic meaning of insulin initiation (e.g. feelings of failure/self-blame or increased diabetes severity)." (PMID 24902877, 2014). "While not a completely effective means of treating diabetes, the enhanced release of insulin early on in the disease pathogenesis has been known to ameliorate hyperglycaemia." (PMID 25070239, 2014). "Diabetic mellitus is an endocrine disorder characterized by insufficiency in circulating plasma level of insulin (Type 1, or Insulin-Dependent Diabetes Mellitus; IDDM) and peripheral resistance and insensitivity to insulin (Type 2, or Non-Insulin-Dependent Diabetes Mellitus; NIDDM)." (PMID 24918092, 2014). "A study of six patients with type 2 diabetes mellitus also revealed that bezafibrate did not change peripheral insulin sensitivity assessed by glucose clamps." (PMID 25360162, 2014). "Uncontrolled diabetes (no insulin treatment) was associated with the development of AD, whereas individuals with controlled diabetes showed no increased dementia, suggesting a role of impaired insulin signaling in the development of neurodegeneration and AD." (PMID 24764191, 2014). "Fourth, for diabetes mellitus, our measure of physician response was not applicable to patients with insulin treatment as data on day-to-day adjustments of dosages were not reliably recorded." (PMID 25027581, 2014). "Patients with declining insulin secretion will develop diabetes earlier when they are insulin resistant rather than insulin sensitive." (PMID 23413806, 2013). "Generally, both positive and negative concerns and beliefs about diabetes and insulin were the basis of the participants’ decision to use insulin in this study." (PMID 24164794, 2013). "While altered insulin signaling is known to be the key factor in the development of diabetes, the role that it plays in diabetic neuropathy (DN) is not well understood." (PMID 24252636, 2013). "While this study did not specifically examine serum insulin, independent of blood glucose or diabetes, it is recognized that insulin resistance (IR) and consequent hyperinsulinemia are central molecular pathologies in the genesis of the metabolic syndrome." (PMID 24204385, 2013). "The discovery of sodium-glucose co-transporter 2 (SGLT2) inhibitors, with a novel mechanism independent of insulin secretion or sensitization, bring about a new therapeutic approach to the management of type 2 diabetes mellitus." (PMID 24341330, 2013). "In this instance, insulin cannot be considered as the best option in treating diabetes in resource-poor settings, because the environment does not support it due to lack of infrastructure." (PMID 23561029, 2013). "The fact that an early treatment with insulin in diabetes mellitus type 2 does not improve endothelial function is in line with a recent study in human, in which flow-mediated dilation remained unchanged after initiation of insulin therapy." (PMID 23497197, 2013). "Diabetic patients were more likely to have proteinuria, glycosuria, and diabetic histories including diagnosed diabetes, insulin therapy, anti-diabetic drug, and nondrug anti-diabetic therapy." (PMID 24033926, 2013). "Dehydration, a well documented risk associated with long-distance air travel, is accentuated in patients with diabetes; and extreme dehydration without proper insulin adjustment has been reported to trigger DKA." (PMID 24360506, 2013).
diabetes (continued). "For type 1 diabetes, HbA1C was never questioned as an appropriate outcome for insulin therapy, but it was non-accepted for two of three type 2 oral diabetes drugs." (PMID 24341379, 2013). "In contrast, for women, the proportion of those with diabetes with CAC was not statistically different from those who were insulin sensitive or insulin resistant with CAC (p≥0.39)." (PMID 23341938, 2013). "Compared with Zucker fatty rats, male ZDF rats become less obese but more insulin resistant, and then rapidly progress to frank diabetes because of the lack of sufficient insulin secretion required adequate compensation for the insulin resistance." (PMID 23671868, 2013). "There are two main forms of diabetes mellitus; type 1 diabetics do not produce insulin and must receive exogenous insulin through injections or an insulin pump." (PMID 24175301, 2013). "The pattern was somewhat different among Asian Indians, who had higher FMD for the IFG and diabetes groups compared with the normal glucose group, not explained by medication use, insulin levels, or BMI." (PMID 23525433, 2013). "None of the 16 T2DM women were on insulin, three women were on oral hypoglycemic agents (1 Glucotrol, 2 Glucophage), and the remaining 12 were not on medications and had undiagnosed diabetes before study entry." (PMID 23781323, 2013). "I took insulin because the pills were not working anymore” (5 years of insulin use/ 2 years of having diabetes)." (PMID 24164794, 2013). "In vivo, there is a good documented association of hypoadiponectinemia with insulin resistance and diabetes mellitus type 2, but the effect of insulin therapy on serum levels of adiponectin is not well studied so far." (PMID 23497197, 2013). "As a result of insulin resistance, patients with T2DM require higher concentrations of insulin to stimulate peripheral glucose uptake and to suppress hepatic glucose production, than are needed in patients without diabetes." (PMID 24499517, 2013). "These women had no prior overt diabetes and shared certain characteristics, that is, no family diabetes history, age over 35, normal prepregnancy BMI, need for insulin therapy as of the early weeks of pregnancy, and high-titer anti-GAD antibody positivity." (PMID 23606858, 2013). "Absolute and relative costs for insulin and CSII were higher in study patients with long diabetes duration compared with a previously analyzed pediatric cohort of DPV patients <20 years of age with on average half the diabetes duration." (PMID 23967077, 2013). "This cohort was insulin-naive, had a mean diabetes duration of 9 years, and had failed to maintain glycemic control during treatment with MET plus SFU." (PMID 23256660, 2013). "Diabetes is a group of chronic carbohydrate metabolism disorders resulting from diminished or absent action of insulin by altered secretion, decreased insulin efficacy or combination of both the factors leading to hyperglycemia." (PMID 23351604, 2013). "And unlike in diabetes, which calls for repeated administration of chitosan-gold insulin nanoparticles, there is greater safety with a single injection of chitosan-gold hormonal nanoparticles." (PMID 23468918, 2013). "Although the majority of cardiovascular effects of exercise is dependent on improvements in blood glucose or insulin, exercise-mediated benefits in human diabetes can be independent of such changes in glycemic parameters." (PMID 23936397, 2013). "RBP4 concentrations in patients with diabetes were not correlated with insulin sensitivity as calculated by the HOMA-IR (r = 0.473, p = 0.218)." (PMID 24099047, 2013). "In this study, we demonstrate an essential role for HCF-1 in glucose-stimulated insulin secretion in the INS-1 pancreatic β-cell line suggesting that HCF-1 represents a promising future therapeutic target for the prevention and treatment of diabetes." (PMID 24250814, 2013).
diabetes (continued). "In type 1 diabetes, or insulin dependent diabetes mellitus, the body has little or no insulin secretory capacity and depends on exogenous insulin to prevent metabolic disorders and death." (PMID 23641947, 2013). "Since no known interaction on pharmacokinetic level are expected between diazepam and insulin it was not considered that insulin treatment in 3 women in diabetes group had effect on concentration data." (PMID 24134697, 2013). "A concern regarding the potential for sulphonylurea-induced cardiovascular toxicity was first raised as a result of the University Group Diabetes Program (UGDP) study, in which an increase in mortality was observed with tolbutamide compared to both insulin and to placebo." (PMID 23286208, 2013). "Past studies have reported that TLQP-21 could stimulate insulin secretion in pancreatic cells and protect these cells from apoptosis, which suggests that TLQP-21 has a potential function in diabetes therapy." (PMID 24278172, 2013). "Among patients initially taking insulin plus oral medications, 11.1 % and 50 % had no need for diabetes medications 6 months after adjustable gastric banding and gastric bypass, respectively." (PMID 23515973, 2013). "Recent findings strengthen the case for insulin as therapy for AD afflicted individuals with or without diabetes (Subramanian and John 2012 ▶)." (PMID 25050258, 2013). "Too few physicians are appropriately intensifying diabetes management through insulin initiation, and aggressive therapeutic treatment is lacking." (PMID 23433347, 2013). "The approach of pairing family physicians with diabetes experts and community retail pharmacists as a facilitating infrastructure to enhance insulin prescribing behaviour in family practice was not successful." (PMID 23433347, 2013). "Participants with early stage diabetes (shortest duration, not treated with insulin, good baseline glycemic control) were the most to benefit from ILI." (PMID 23840207, 2013). "These factors also allayed their negative concerns and beliefs towards diabetes and insulin, which were their barriers for insulin acceptance as it caused fear to use insulin." (PMID 24164794, 2013). "In diabetes, glucagon secretion is not suppressed at high glucose, exacerbating the consequences of insufficient insulin secretion, and is inadequate at low glucose, potentially leading to fatal hypoglycemia." (PMID 24315372, 2013). "In summary, we found that a diagnosis of diabetes (insulin or oral dependent) did not affect outcomes in general surgical patients." (PMID 24455308, 2013). "The TNM tumor stage of patients with breast carcinoma and diabetes mellitus at diagnosis was not higher among 13 patients on glargine compared to 69 patients on other types of insulin." (PMID 24131755, 2013). "Neonatal exendin-4 treatment also improves insulin secretion and glucose tolerance in adolescent and adult rat progeny following IUGR, preventing development of diabetes in these animals, although the effects during treatment were not measured in the latter study." (PMID 23424667, 2013). "The basis of the diabetes therapy is to replace the lack of insulin by regular exogenous insulin infusion with a right dosage each time, for keeping the patients alive." (PMID 24163813, 2013). "This pre-planned meta-analysis shows that similar improvements in HbA1c can be achieved with fewer hypoglycaemic episodes, particularly nocturnal episodes, with IDeg than with IGlar across a broad spectrum of patients with diabetes (particularly T2DM patients), and insulin regimens." (PMID 23130654, 2013). "The findings in human subjects were further supported in experimental animal models demonstrating impaired expression of HSP-72 in the rat model of streptozotocin-induced diabetes and reduced expression of both HSP-25 and HSP-72 in the insulin-resistant aged rats." (PMID 23894433, 2013).
diabetes (continued). "Four different subjects were not taking medication for diabetes (insulin or oral antihyperglycemic medication) and were presumably diet controlled as only one of these 4 had a hemoglobin A1C over 8.0%, demonstrating suboptimal control." (PMID 23431420, 2013). "At the same time, mortality from neoplasms decreased among people without diabetes and showed also a decreasing trend among people with non-insulin treated diabetes." (PMID 23837500, 2013). "None of our subjects developed diabetes, nor did we observe significant changes in the concentrations of fasting glucose, insulin, and C-peptide." (PMID 23866300, 2013). "Compared with insulin starters, those starting a GLP-1 receptor agonist had better glycaemic control and had higher BMI at baseline, and were younger with shorter duration of diabetes." (PMID 23330649, 2013). "An insulin support program utilizing diabetes experts and community retail pharmacists to enhance insulin prescribing in family practice was not successful." (PMID 23433347, 2013). "The proportion of insulin premix use was relatively consistent regardless of the duration of diabetes, ranging from 62.91% to 67.50% with no discernible pattern across the duration of the disease." (PMID 23800082, 2013). "In animals with a duration of diabetes of more than 4 weeks, insulin producing β-cells were completely absent." (PMID 23762878, 2013). "Interestingly, it shares many properties, such as potentiating glucose-stimulated insulin secretion, improving glycemic control, and reducing islet cell apoptosis, with GLP-1 receptor agonists, which have been widely used in diabetes therapy." (PMID 24278172, 2013). "Therefore, we evaluated a new insulin resistance index based on C-peptide levels measured during a MTT and glucose clamps in Japanese patients with type 2 diabetes mellitus." (PMID 23339473, 2013). "Since the mean duration of known diabetes in the T2D patients was 4 years and none were treated with exogenous insulin, most likely β-cell function was impaired but not abolished." (PMID 23401789, 2013). "Recently, leptin has been shown to suppress glucagon and correct diabetes in mice, in the absence of insulin." (PMID 23132340, 2013). "Accumulating evidence suggests endoplasmic reticulum (ER) stress plays a substantial role in the pathogenesis of diabetes and contributes to insulin resistance, and it has been established that several PPAR α/γ dual agonists enhance insulin sensitivity by inhibiting ER stress." (PMID 24244369, 2013). "Phosphorylation of P38 was responsive to insulin stimulation in the retina but not the liver in a mouse model of diabetes." (PMID 23326243, 2013). "In 2003–2007, for example the excess mortality from CHD was almost eightfold for women and almost fivefold for men with insulin-treated diabetes compared to people without diabetes." (PMID 23837500, 2013). "Unlike, HNF1A and HNF4A monogenic diabetes, pancreatic atrophy is common in those with HNF1B mutations, therefore carriers do not display the same sensitivity to SU therapy and often require insulin therapy." (PMID 23766565, 2013). "In contrast, Japanese diabetes therapeutic guidelines do not clearly specify the timing or methods for insulin initiation and intensification, although the guidelines recommend achieving goal glycemic values." (PMID 24011395, 2013). "The SDT rat is a new model of nonobese, severe type 2 diabetes mellitus with hyperglycaemia, hemorrhage in and around the islets, and hyposecretion of insulin (hypoinsulinemia) resulting from a significantly decreased number and size of islets." (PMID 23691528, 2013). "Our data suggest that levels of SPARC are reduced in islets from donors with diabetes and that it has a role in insulin secretion, an effect which appears independent of SPARC’s modulation of obesity-induced insulin resistance in adipose tissue." (PMID 23840838, 2013).